KLF4 (KLF transcription factor 4)
Diseases named in the same sentence as KLF4 in open-access papers (continued):
Sharing a sentence is not in itself a finding about the gene and the disease.
tumor (continued). "KLF4 is a transcriptional regulator known to maintain stemness and found to perform both oncogenic and tumor suppressor functions in a variety of cancers, including but not limited to bladder, esophageal, and gastric cancers." (PMID 36686824, 2022). "In HPV-positive tumor tissue samples a strong KLF4 positive nuclear staining reaction all over the cancer cell nest combined with a membranous E-cadherin reaction was detected." (PMID 35219646, 2022). "DUB3 inhibited HCC cell proliferation in vitro and tumor growth in vivo while enhancing the chemosensitivity of HCC cells in a KLF4-dependent manner." (PMID 35383144, 2022). "The transcription factor Krüppel-like factor 4 (KLF4) is best known as a determinant of cell stemness and a tumor suppressor." (PMID 35852857, 2022). "Numerous studies are needed to find out the role of KLF4, and the molecular basis of the transformation between tumour suppressor genes and oncogenes still needs to be solved." (PMID 35177016, 2022). "The intervention of sh-CHRM3-AS2 also significantly down-regulated CHRM3-AS2 and KLF4 expression and up-regulated miR-370-5p expression in tumour xenografts (P < 0.01)." (PMID 35359381, 2022). "Our work proposing that KLF4 can impair AR adds another layer of complexity to KLF4 tumor suppressive function in controlling prostatic cell proliferation and survival." (PMID 33640491, 2021). "Pparγ binding to Klf4 promoter induces the tumor suppression activity by affecting the complex pathways involving Klf4 in tumorigenesis as well as adipogenesis." (PMID 34195082, 2021). "Kruppel-like factor 4 (KLF4) has been considered as a tumor-suppressive transcription factor in PaC." (PMID 33799952, 2021). "KLF4 plays a critical yet highly context-dependent role in the induction and maintenance of CSCs in different tumors, while it exerts tumor suppressor function in others." (PMID 34638302, 2021). "Previous studies have reported that KLF4 is a tumor-suppressor TF that, once upregulated, inhibits cell growth and induces cell cycle arrest." (PMID 33568674, 2021). "Consistently with the concentration of cholesterol in tumor tissues of xenografts, the SQLE, phosphorylated PI3K, and CSC‐associated c‐Myc and KLF4 proteins displayed the corresponding changes in line with the tumor growth in each group of xenografts." (PMID 33511005, 2021). "NEDD9 overexpression significantly enhanced tumor sphere formation, and also elevated the expression of stemness-related transcription factors, including KLF4 and ALDH1A3." (PMID 33710809, 2021). "Mounting evidence supports the notion that aberrant BMI1 and KLF4 expression are responsible for tumor generation, metastasis, and treatment failure." (PMID 33828977, 2021). "TRAF6 binds to and ubiquitinates Krüppel-like factor 4 (KLF4), a complex transcription factor that acts as a tumor-promoting gene in NPC." (PMID 33436584, 2021). "Immunofluorescence staining performed on three of the tissue samples showed co-expression of OCT4 and c-MYC with NANOG, SOX2 and KLF4 by tumor gland cells, and expression of OCT4 and c-MYC exclusively by cells within the stroma." (PMID 34685477, 2021). "c-MYC (green) was also co-expressed with NANOG (red), SOX2 (red) and KLF4 (red) by cells within the tumor glands (arrowheads)." (PMID 34685477, 2021). "Similar to previous studies, SPP1, MTHFD2, TRIP13, MKI67, MMP9, and KLF4 were some of the most clinically valuable tumor markers, especially in CC and EC." (PMID 34834529, 2021). "The interaction partner and cell type determine role of KLF4 as a tumor-suppressing or tumor-promoting factor." (PMID 33921908, 2021). "Our experiments regarding the effects of glucose starvation reveal that KLF4 acts as a tumor suppressor by increasing autophagic cell death." (PMID 33917010, 2021).
tumor (continued). "As one of the four factors (SOX2, C-Myc, OCT-4, and KLF4) required for reprogramming adult fibroblasts and skin melanocytes into induced pluripotent stem cells (iPS), KLF4 plays an essential role in tumor initiation and cancer stemness." (PMID 33726845, 2021). "The cooperation of METTL3 with the reader protein YTH N6-Methyladenosine RNA Binding Protein 2 (YTHDF2) leads to the degradation of Klf4, which diminishes the tumor suppression activity of Klf4 and consequently induces cancer progression." (PMID 34195082, 2021). "The authors firstly demonstrated that PTTG1 marks some specific OCT4- and KLF4-positive tumor cells, mainly localized at the periphery of the neoplasm." (PMID 34209730, 2021). "Since NANOG, SOX2 and KLF4 are essential for converting tumor cells into aggressive stem-like cells, an increase in the expression of these markers in our study after irradiation further supports the increased cancer stem cell population." (PMID 33419140, 2021). "For assessing the significant correlation of KLF4 and IL-1β with tumor purity and tumor-infiltrating functional immune cells in LUAD and LUSC, TIMER database was queried." (PMID 34440860, 2021). "Both KLF4 and Slug showed a gradient, a decreasing one of KLF4 from the middle to the border of the tumor cell nest, and an increasing one of the nuclear reactions of Slug from the middle of the tumor cell nest to the border." (PMID 33802627, 2021). "Some studies have found that KLF4 is downregulated in lung cancer, concluding a role in tumor suppression in lung tissue." (PMID 34685477, 2021). "Collectively, these data demonstrate that USP11 down‐regulation sensitizes human HCC cells to apoptosis and suppresses tumour growth by regulating KLF4 stability." (PMID 34114341, 2021). "With the decrease in H3K4me1 level at enhancers, transcription factors such as LIFR and KLF4 were markedly downregulated, effectively inhibiting tumor progression." (PMID 34758724, 2021). "By co-culturing ESCC cells with G-MDSC, we observed enhanced NEDD9 expression, tumor sphere formation, and expression of stemness-related transcription factors, KLF4 and ALDH1A3." (PMID 33710809, 2021). "KLF4: KLF4 is a transcription factor attributed to bifunctional roles in cancer, as a potent tumor suppressor or as an oncogene." (PMID 33412518, 2021). "Overexpression of KLF4 was shown to promote osteosarcoma cancer stem cells and act as a tumor promoting gene in nasopharyngeal carcinoma." (PMID 34195082, 2021). "Through these interactions, LETR1 controls intricated transcriptional networks to fine-tune the expression, above all, of essential proliferation- and migration-related genes, including the tumor-suppressor TF KLF4 and the semaphorin guidance molecule SEMA3C." (PMID 33568674, 2021). "Further experiments indicated that circUBAP2 promoted malignant biological behavior of NSCLC tumor cells by targeting KLF4 through modulating miR-3182 expression." (PMID 33882454, 2021). "Thereafter, we comprehensively evaluated the associations between tumor location (embryological origin), pathological diagnosis (histological type), and driver mutations including AKT1, KLF4, SMO, POLR2A, and NF2 mutations." (PMID 33772057, 2021). "On the contrary, the loss of KLF4 weakened the inhibition of N-cadherin, MMP2, and MMP9, leading to increased tumor cell invasion and migration, thereby affecting survival and prognosis." (PMID 34367275, 2021). "In tumor tissue not only the KLF4 levels are lower compared to normal tissue, but its expression is inversely correlated with the stage of tumors and survival." (PMID 33802627, 2021). "IF staining demonstrated co-expression of OCT4 (green) with NANOG (red), SOX2 (red) and KLF4 (red) by cells within the tumor glands (arrowheads)." (PMID 34685477, 2021).
tumor (continued). "Further, it has been found that KLF4α is highly expressed in tumors and although KLF4 (FL) exerts tumor inhibitory effects, but excessive KLF4α opposes its effect, thereby promoting tumorigenesis." (PMID 34440860, 2021). "In cancer, particularly non-small cell lung cancer (NSCLC), Klf4 expression is downregulated in comparison to the surrounding normal tissues, indicative of a tumor suppressive function." (PMID 34195082, 2021). "Krüppel‐like factor 4 (KLF4) is a zinc‐finger containing DNA‐binding transcription factor involved in tumorigenesis and acts as a tumour suppressor or an oncogene depending on the tissue." (PMID 34114341, 2021). "We tested the expression of BMI1 and KLF4 of primary and metastasis tumor in mouse OS xenografts, and the IHC results demonstrated that the expression of BMI1 and KLF4 was higher in metastasis tumor than that in primary (**p < 0.01; ***p < 0.001)." (PMID 33828977, 2021). "Kruppel-like factor 4 (KLF4) can act as an oncogenic or a tumor-suppressive transcription factor depending on the type of cancer." (PMID 33435156, 2021). "The oncogenic nature of KLF4 in NSCLC is quite contradictory, as most of the studies have depicted the tumor suppressive role of KLF4 in NSCLC." (PMID 34440860, 2021). "The enhanced expression of pluripotency-related transcription factors, such as KLF4 and Myc, has been shown to transform differentiated tumor cells into cells with CSC properties." (PMID 34638302, 2021). "APTO-253 is a small molecule that inhibits c-Myc expression and mediates anticancer activity through induction of KLF4-mediated tumor suppression." (PMID 34568499, 2021). "KLF4 exhibits cancer suppressive effects in gastrointestinal tumors, and its absence often leads to tumor deterioration." (PMID 34367275, 2021). "All 12 cases stained positively for KLF4 which was consistently seen in the cytoplasm of tumor cells and the cytoplasm of stromal cells adjacent to tumor glands in six of the 12 cases." (PMID 34685477, 2021). "UALCAN was used to compare the effects of different drinking frequencies for tumor patients on the expression levels of KLF4 and KLF5 in ESCA." (PMID 34367275, 2021). "Our group reported a novel tumor suppression function for the transcription factor KLF4 in pediatric T-ALL." (PMID 34504651, 2021). "Here, we demonstrate the presence of an OCT4+/SOX2+/KLF4+/c-MYC+ CSC subpopulation within the tumor nests (TNs) and another within the peritumoral stroma (PTS), in this tumor." (PMID 32019273, 2020). "Interaction with these partners such as TEAD1–4, RUNX, KLF4 and AP-1 promotes tumor growth, metastasis and immune evasion." (PMID 33097055, 2020). "In line with the in vitro findings, napabucasin down-regulated Nanog, SOX2, Klf4 and Oct4 in the tumor cells, and also decreased the proportion of Ki67+ tumor cells." (PMID 33343368, 2020). "As expected, in rescue experiments, silencing SETD7 or KLF4 abrogated the tumour‐suppressive phenotypes by depletion of METTL3." (PMID 32126149, 2020). "Traditionally, the role of KLF4 in cancer has been to act primarily as a tumor suppressor, that is, to drive terminal differentiation and inhibit cellular proliferation." (PMID 33266506, 2020). "The pro-oncogenic role of KLF4 has been demonstrated in MM cell lines, while the tumor initiation and maintenance role of SOX2 has also been well-documented." (PMID 32019273, 2020). "The demethylating agent 5-azacitidine (Aza) was shown to upregulate KLF4 expression in other tumor entities." (PMID 32944247, 2020).
tumor (continued). "miR-25 was further shown as overexpressed in NSCLC compared with paired normal lung tissues, and demonstrated to activate ERK signaling via KLF4, a miR-25 target gene, leading to increased tumor cell migration and invasion." (PMID 32971741, 2020). "Our work demonstrated that both CD9 and CD81 are directly transcriptional targets of KLF4, which has been recognized and addressed as a tumor suppressor in various cancers." (PMID 32350244, 2020). "There is a marked decrease in KLF4 expression in CRC tumor samples obtained from patients, which is also observed in the mouse model." (PMID 33266506, 2020). "For instance, KLF4 can function as an oncogene or a tumor suppressor depending on the type of cancer involved." (PMID 32937756, 2020). "The expression of Ki-67 and KLF4 was decreased in the tumor tissues of the sh-CDR1as group as compared with that in the control group." (PMID 33052880, 2020). "In the onco-genetic context, KLF4 acts as a tumor suppressor in colon cancer, but plays a potent oncogenic role in mammary carcinoma and melanoma." (PMID 32245394, 2020). "KLF4 is important in regulating response to many known drugs, and it also plays a role in tumor microenvironment." (PMID 33266506, 2020). "The re-expression of KLF4 sensitized tumor cells in the PDX model towards systemic chemotherapy in vivo." (PMID 32944247, 2020). "Our study shows a novel function for KLF4 in modulating the de-differentiation of tumor cells and the induction of EpCAM+/CD133+ LCSCs in HuH7 cells." (PMID 32408542, 2020). "The accumulated expression of SETD7 and KLF4 upon METTL3 depletion was also discovered in UM‐UC‐3 derived xenograft tumours obtained from nude mice." (PMID 32126149, 2020). "In different kinds of tissues, KLF4 plays different roles, either acting as an oncogene or as a tumor suppressor." (PMID 32756012, 2020). "It was reported that sustained KLF4 expression promotes ineffective tumor angiogenesis and diminishes tumor growth." (PMID 32756012, 2020). "Although KLF4 was initially defined as a tumor suppressor, the oncogenic role of KLF4 has become clearer in recent years." (PMID 33052880, 2020). "We demonstrate here that KLF4 expression reduces tumor growth and enhances the chemotherapeutic response in this tumor model." (PMID 32944247, 2020). "The study revealed that KLF4 was not only a tumor suppressor in HCC but also can be regarded as a valuable prognostic factor and potential biological target for diagnosis and treatment in HCC patients." (PMID 32756012, 2020). "Collectively, our data suggest a novel function for KLF4 in modulating the de-differentiation of tumor cells and the induction of EpCAM+/CD133+ LCSCs in HuH7 HCC cells." (PMID 32408542, 2020). "The reduced expression of KLF4 in human CRC tissues has been associated with increased growth of CRC cells, lymphatic node metastasis, reduced tumor cell differentiation, and tumor recurrence." (PMID 33266506, 2020). "This compound inhibits HCC self-renewal and tumor initiation through suppression of gene (Oct4, KLF4, Nanog, and SOX2) and surface marker (CD133+/ALDH1+) expression of LCSCs." (PMID 32466488, 2020). "KLF4 is a crucial regulator of normal cell proliferation and it can be a tumor suppressor or an oncogene, depending on the tissue, tumor type, or cancer stage." (PMID 32443915, 2020). "Aza has previously been shown to upregulate KLF4 in other tumor entities and we demonstrate that this ability is maintained in B-ALL." (PMID 32944247, 2020). "KLF4 wasdown-regulated in both tumor samples and mammospheres.Meanwhile, expression of NANOG was not changed inmammospheres, but it was down-regulated in tumors.Among EMT-related genes, CDH2, SNAIL1, TWIST1/2 andZEB1 were also overexpressed in mammospheres." (PMID 31376329, 2020). "Immunofluorescence (IF) staining demonstrated an OCT4+/SOX2+/KLF4+/c-MYC+ CSC subpopulation within the tumor nests (TNs) and another within the peritumoral stroma (PTS) of HNmMM tissues." (PMID 32019273, 2020).
tumor (continued). "It has been a technical challenge in the field to determine the relevance of KLF4‐mediated genome stability in cancer formation due to KLF4’s ambivalent role in tumorigenesis as either a tissue‐specific tumor suppressor or an oncogene." (PMID 33231937, 2020). "Judging from clinical and experimental data, KLF4 has an anti-cancer effect on suppressing tumor differentiation, proliferation, invasion, epithelial-mesenchymal transition (EMT), and metastasis." (PMID 32756012, 2020). "In the case of KLF4, co-stained cells as well as cells, which were solely positive for MCT1 or KLF4, existed within the tumor sections." (PMID 32872409, 2020). "KLF4 is a direct target of miR-543, miRNA highly expressed in CRC samples and cell lines, and associated with tumor size, TNM stage and metastasis." (PMID 33266506, 2020). "Immunohistochemical (IHC) analysis was applied to detect the protein expression of Ki-67, which is a marker for the proliferation of human tumor cells, and KLF4 in xenografted tumors of each group." (PMID 33052880, 2020). "In summary, KLF4 serves as a tumor suppressor in CRC and sensitizes CRC cells to various forms of treatment." (PMID 33266506, 2020). "KLF4 can function as an oncogene or tumor suppressor in a highly tissue-specific cell-dependent manner." (PMID 32408542, 2020). "METTL3 also catalyzes m6A modifications in the mRNAs of SETD7 and KLF4, two tumor suppressors that are part of the METTL3/YTHDF2-SETD7/KLF4 m6A axis." (PMID 32765970, 2020). "Both Klf4 overexpressing mice and p120 catenin knockout have robust NFκB activation that is an early event, and in Sox2 knockout mice, tumor progression correlates with inflammation." (PMID 30998758, 2019). "We found that KLF4 expression is lost in tumor sections obtained from CRC patients and in those of mouse colon following azoxymethane and dextran sodium sulfate (AOM/DSS) treatment when compared to their respective normal appearing mucosa." (PMID 32566755, 2019). "Clinical evidence suggests that KLF4 is a potent tumor repressor, but in addition, KLF4 recently has been seen to act as an oncogenic element in various cancers." (PMID 31040909, 2019). "KLF4 demonstrates low expression in a variety of cancers and therefore has been considered a tumor suppressor." (PMID 31040909, 2019). "Statistical analysis showed that the expression levels of KLF4 and vimentin are negatively correlated in normal mucosa (P < 0.05) and in tumor sections (P < 0.001)." (PMID 32566755, 2019). "Immunohistochemistry analyses showed that KLF4 was presented in the cytoplasm and nuclear of tumor cells and exhibited stronger staining in tumor tissues from patients with a better prognosis." (PMID 31623606, 2019). "The combined treatment with radiation and rhEpo significantly increased the number of Klf4-positive tumor cells (2.16-fold, p = 0.019, unpaired, two-sided Student’s t test)." (PMID 30700319, 2019). "Five days after irradiation, tumors were explanted and tumor sections stained for Sox2 and Klf4 and subjected to an automated image analysis." (PMID 30700319, 2019). "Krüppel-Like Factor 4 (KLF4) is a member of the KLF transcription factor family, and evidence suggests that KLF4 is either an oncogene or a tumor suppressor." (PMID 31040909, 2019). "Mounting evidences from both experimental and clinical data have suggested that KLF4 functioned as a tumor suppressor in cancers and played a critical role in tumor differentiation, EMT, invasion and metastasis." (PMID 29748877, 2019). "Consistently, the levels of KLF4 and Slug in tumor tissues from the mice administrated by SNS-032 were also appreciably reduced than those from the mice treated with vehicle." (PMID 31526394, 2019).